FAIM2 (Fas apoptotic inhibitory molecule 2)
Diseases named in the same sentence as FAIM2 in open-access papers (continued):
Sharing a sentence is not in itself a finding about the gene and the disease.
tumor (continued). "In addition, we explored the correlation between FAIM2 expression and tumor immune cell infiltration by the TIMER2 database." (PMID 36185230, 2022). "By exploring the association between FAIM2 expression and multiple clinicopathological characteristics of NSCLC patients, we discovered that FAIM2 was an independent factor correlated with the tumor stage (P = 0.0024), lymph node metastasis (P = 0.0161), and bone metastasis (P = 0.0010)." (PMID 34568020, 2021). "Recent studies reported that FAIM2 participates in regulating tumor initiation and progression." (PMID 34568020, 2021). "However, those previous studies focused on the upstream regulation of FAIM2, and ignored the downstream effectors of FAIM2 in tumor cells." (PMID 34568020, 2021). "FAIM2 inhibition showed modest but significant tumor killing effect (p < 0.05)." (PMID 27677402, 2016). "This suggests that inhibition of anti-apoptosis molecules by FAIM2 may restore repressed apoptosis signaling and eventually lead to tumor cell death." (PMID 27677402, 2016). "However, the role of FAIM2 in tumor prognosis and immune infiltration has rarely been studied." (PMID 36185230, 2022). "Thus hyper-methylation and downregulation of FAIM2 can help the tumour to evade apoptosis." (PMID 36329447, 2022). "Further assessment were also reinvestigated, patients showing lower expression had poor disease prognosis (log rank p = 0.01) than patients with higher expressions of NPY and FAIM2 in their tumours, which could be indirectly controlled by differential methylation." (PMID 36329447, 2022). "We then analyzed whether a knock-down of FAIM2 can reduce the tumor growth." (PMID 27677402, 2016). "In this study, we found that FAIM2 regulated the EMT process and Wnt pathway to promote tumor proliferation and metastasis." (PMID 34568020, 2021). "In conclusion, our research showed that FAIM2 was significantly upregulated in NSCLC tissues and performed an oncogenic function in tumor progression, including tumor cell proliferation and bone metastasis." (PMID 34568020, 2021). "Our study shows that FAIM2 expression is positively correlated with CD8+ T cell infiltration but negatively correlated with MDSC infiltration in most tumors, which indicated that FAIM2 mainly plays a role in anti-tumor immunity in various cancers." (PMID 36185230, 2022). "Moreover, we were able to identify a segregated tumor cell cluster with co-expression of GD2, CD56, B7-H3, CD24 and FAIM2 (orange cluster)." (PMID 34503120, 2021). "Although this is statistically significant for tumor killing effect, FAIM2 inhibition alone would not be enough for SCLC treatment." (PMID 27677402, 2016). "Furthermore, we also observed that Faim2-expression was down-regulated in tumour tissues by 87% compared to 94% upregulation in adjacent normal part of normal tissues." (PMID 36329447, 2022). "Moreover, FAIM2 transcription was enriched in primary tumor cells without MYCN amplification as compared to those with MYCN amplification, thus supporting previous findings." (PMID 34503120, 2021).
cancer (11 papers, 2019 to 2024). A tumor composed of atypical neoplastic, often pleomorphic cells that invade other tissues. "The FAIM2 expression was down-regulated in most tumors and highly expressed FAIM2 was associated with a better prognosis in several cancers." (PMID 36185230, 2022). "For instance, a study showed that over-expression of FAIM2 was associated with adverse clinical prognosis in LC, and knockout FAIM2 could inhibit anoikis resistance and cancer cell viability." (PMID 36713571, 2022). "In addition, FAIM2 is significantly differentially expressed across immune subtypes and molecular subtypes of most cancer types, which may demonstrate that FAIM2 is a promising diagnostic pan-cancer biomarker and is involved in immune regulation." (PMID 36185230, 2022). "All these results indicated that FAIM2 expression was significantly correlated with the immune infiltration in cancers." (PMID 36185230, 2022). "Our study identified novel differentially methylated genes (mainly NPY and FAIM2) and also validated the previously identified differentially methylated CpG sites associated with PDAC cancer patient’s survival." (PMID 36329447, 2022). "All these results indicated that FAIM2 expression differs in molecular subtypes and immune subtypes of various human cancer types." (PMID 36185230, 2022). "The normal tissue samples in GTEx cohort had higher average expressions of both NPY and FAIM2 than in comparison with cancer samples in the TCGA cohort." (PMID 36329447, 2022). "Taking these facts together, FAIM2 is a promising and prospective therapeutic target for cancer, as well as a marker for both clinical outcomes and immune infiltration." (PMID 36185230, 2022). "FAIM2 expression is closely related to TMB, MSI, and MMR, which proved that FAIM2 is closely related to the TME in human cancers." (PMID 36185230, 2022). "In this study, we conducted a comprehensive pan-cancer analysis and thoroughly investigated the role of FAIM2 in cancers." (PMID 36185230, 2022). "To systematically investigate the role of FAIM2 in tumors, we conducted a pan-cancer analysis of it using large-scale RNA-sequencing (RNA-seq) data from various public databases." (PMID 36185230, 2022). "In this study, the role of FAIM2 in prognosis and immune infiltration in human cancers was comprehensively analyzed." (PMID 36185230, 2022). "Then, FAIM2 anti-apoptotic activity has been found to have a role in certain types of cancer, such as non-small cell lung cancer, hepatocellular carcinoma and breast carcinoma." (PMID 36185230, 2022). "The results showed that low expression of FAIM2 is related to a poor prognosis in some cancer types." (PMID 36185230, 2022). "To systematically explore the role of FAIM2 in tumors, we performed a pan-cancer analysis." (PMID 36185230, 2022). "Furthermore, we conduct a GSEA enrichment analysis between the FAIM2 high expression group and FAIM2 low expression group in 33 kinds of cancers, and most results of them were involved in immunity." (PMID 36185230, 2022). "The expression levels of FAIM2, NPY, and FOXE1 were also compared in the cancer samples with normal samples in validation cohort 3 and a negative relationship between methylation and gene expression was observed." (PMID 36329447, 2022). "For the remaining gDMs (NPY, FOXE1, FAIM2, and KCNA6), we found hyper-methylation in PDAC, as confirmed by the higher extent of methylation in cancer samples." (PMID 36329447, 2022). "The hub genes identified by PPI network analysis include SYN1, CNTN2, FAIM2, MT3, and SH3GL2, which are involved in the pathogenesis of different cancers." (PMID 32328342, 2020). "In addition, our result reveled that FAIM2 expression is negatively related to TMB, MSI, MMR, and DNA methylation in most cancer types." (PMID 36185230, 2022).
cancer (continued). "In our study, ESTIMATEScore including ImmuneScore and StromalScore have a positive connection with FAIM2 expression in most cancer types, but have a negative connection in LGG, which could explain why FAIM2 low expression has a connection with poor prognosis in LGG." (PMID 36185230, 2022).
metabolic disease (2 papers, 2014 to 2025). A congenital disorder (due to inherited enzyme abnormality) or acquired (due to failure of a metabolically important organ) disorder resulting from an abnormal metabolic process. "Taken together, these findings suggest that FAIM2 deficiency exacerbates HFD-induced metabolic disorders." (PMID 41057543, 2025). "Although the functions of the FAIM2 in the different metabolic diseases are not well known, it is known that the FAIM2 acts as an antiapoptotic protein which would inhibit Fas-mediated cell death." (PMID 24393375, 2014).
cardiovascular diseases (1 paper, 2014). "However, there are no published studies in humans that have analyzed the association between the FAIM2-rs7138803 polymorphism and resting heart rate, which is an independent and important risk factor of cardiovascular diseases, mainly in type 2 diabetic patients." (PMID 24393375, 2014). "Only one previous study, has examined the association between the FAIM2-rs7138803 polymorphism and cardiovascular disease, and no statistical association was found." (PMID 24393375, 2014).
infection (1 paper, 2025). The state of being infected such as from the introduction of a foreign agent such as serum, vaccine, antigenic substance or organism. "Notably, the anti-apoptotic gene Faim2 was significantly suppressed, suggesting that H10N3 infection may enhance the apoptotic process by inhibiting anti-apoptotic factors." (PMID 40076601, 2025).
FAIM2 also shares sentences with these, for which no sentence is quoted: Hashimoto thyroiditis (2 papers); pancreatic carcinoma (2); prostate carcinoma (2); adrenocortical carcinoma (1); Anxiety (1); asthma (1); autoimmune thyroid disease (1); Cerebellar atrophy (1); cerebrovascular disease (1); cyst (1); deafness (1); ductal carcinoma (1); dyslipidaemia (1); dyslipidemia (1); endometrial cancer (1); esophageal cancer (1); gastric cancer (1); lymph node metastasis (1); lymphoid neoplasm (1); multiple sclerosis (1); myocardial infarction (1); neurodevelopmental disorder (1); neuroendocrine tumor (1); neurofibromatosis type 1 (1); Niemann-Pick disease, type C1 (1); non-alcoholic fatty liver disease (1); obstructive sleep apnea (1); ovarian serous cystadenocarcinoma (1); pheochromocytoma and (1); rectum adenocarcinoma (1).
A further 8 diseases each share a sentence with FAIM2 in 1 paper.